EPHB4 (EPH receptor B4)
Diseases named in the same sentence as EPHB4 in open-access papers (continued):
Sharing a sentence is not in itself a finding about the gene and the disease.
tumor (continued). "In addition, Eph has been reported to suppress the wild type of EGFR pathway, whereas in patients with EGFR-mutation, the EGFR-independent tumor growth-promoting effects may outweigh the inhibitory effects of EphB4." (PMID 34445227, 2021). "We hypothesized that loss of PDCD10 activates GBM cells and tumor progression via EphB4." (PMID 32850441, 2020). "This cytoplasmic localisation of EphB4 in tumour cells contrasts with its known localisation within sites of cell-cell contact between non-transformed epithelial cells and may suggest that active EphB4 signalling has caused endocytosis of the receptor-ligand complex in these cells." (PMID 16171530, 2005). "As expected all EPHB4 wild type CPPL mice had progressive increase in tumor burden (CPPL;EPHB4wt/wt)." (PMID 40044981, 2025). "Secondly, EphB4-ephrin-B2 pathway continue to promote tumor progression even in androgen deprivation and thus hormone refractory tumor." (PMID 40044981, 2025). "EphA2 mediates angiogenesis through its association with cluster of differentiation 44 (CD44) and SRC, while EphB4 promotes tumor angiogenesis by inhibiting the Ras pathway." (PMID 40821121, 2025). "Conditional deleted EphB4 in the prostate epithelium prevented tumor formation in over half the PTEN knock out mouse and first demonstration that EphB4 is required for tumor initiation." (PMID 40044981, 2025). "The simultaneous inhibition of EphB4 and PDGFRβ by dasatinib resulted in a significant decrease in cell viability and tumor growth rate and significantly prolonged survival in vivo." (PMID 40508013, 2025). "We can notice significant fluctuations in EphB4 expression, possibly indicating the presence of a distinct subpopulation of tumor cells." (PMID 40168331, 2025). "Co-treatment with HHT and IM also augmented the sensitivity of K562 cells to IM and the anti-tumor activity of imatinib by blocking the EphB4/RhoA pathway." (PMID 39949739, 2025). "Ephrin type-B receptor 4 (EPHB4) is overexpressed on the surface of various tumor cells, including cells from malignant bone and soft-tissue tumors." (PMID 40842575, 2025). "In conclusion, EphB4-ephrin-B2 pathway is induced early in PC and appears to contribute to tumor initiation and progression." (PMID 40044981, 2025). "Rapid, deep and sustained regression of established tumors supports the sustained contribution of EphB4-ephrin-B2 in tumor progression." (PMID 40044981, 2025). "EPHB4 protein was shown to be overexpressed on the surface of tumor cells in malignant bone and soft-tissue tumors and in breast, ovarian, lung, prostate, and colorectal cancers." (PMID 40842575, 2025). "The expressions of matrix metalloproteinases (MMPs), EphB4 and β-catenin were downregulated in tumor tissues from HepG2 cells and Xenograft model tissues treated with HHT." (PMID 39949739, 2025). "Concordant with our previous findings, downregulation of EphB4 in cancer cells increases local tumor growth in both models." (PMID 39489818, 2025). "Current work first investigated the potential role of EphB4 in tumor initiation first using genetic model of PTEN and EphB4 conditional deletion and subsequent studies of pharmacological inhibitor of the pathway in both tumor initiation and tumor progression." (PMID 40044981, 2025). "EphB4 also contributes to tumor biology, being involved with increased proliferation, motility, and migration of cancer cells." (PMID 40421081, 2025). "Although EphB4-targeting agents show positive effects in reducing tumor growth, especially in combination with radiotherapy, drug specificity remains a significant challenge." (PMID 40421081, 2025). "Previously, induction of EphB4 and role in tumor cell biology has been done in established tumors and tumor cell lines." (PMID 40044981, 2025). "Increased EPHB4 gene expression suggests an intrinsic role of EphB4 in the development of a more aggressive tumor phenotype in CRC." (PMID 38651144, 2024).
tumor (continued). "The EphB4-EphrinB2 interaction between tumor cell-tumor vessel also promotes tumor growth and enhances tumor angiogenesis, and prohibits immune cell trafficking into the tumor." (PMID 38985143, 2024). "In Eph/ephrin signaling, EphA2, EphB4 and EphrinB2 have been extensively studied especially in tumor." (PMID 38630320, 2024). "Although EphB4 overexpression can enhance tumor angiogenesis, the newly formed vascular network is usually dysfunctional and inefficient, unable to meet the demands of cell proliferation." (PMID 38651144, 2024). "Contributing to the complexity is the fact that EphB4 and ephrinB2 can have independent, dichotomous effects on primary tumor growth and metastasis." (PMID 39091728, 2024). "Ongoing research efforts aim at investigating the impact of manipulating EphB4 and ephrinB2 signaling pathways in metastasis and tumor progression." (PMID 39091728, 2024). "Subsequently, the PDGF-BB ligand activates PDGFRβ and EPHB4 through direct and indirect mechanisms, leading to the downregulation of Akt and Erk1/2 pathways, which enhance tumor cell survival and proliferation." (PMID 38233802, 2024). "Our data suggest that EphB4 acts as a tumor suppressor by inhibiting both the growth of primary tumors and the formation of metastases." (PMID 39091728, 2024). "It is worth noting that a number of other drugs developed to target EPHB4 have been shown to inhibit tumour angiogenesis, including VANDETANIB, which has received drug marketing approval." (PMID 39036049, 2024). "Among these 10 genes HDAC1, CASP3, REST, HMG20B, FZD7,GNAI3, FZD1 and EPHB4 had elevated expression in tumor group compared to the normal group, while KCNJ9 and SCRT1 were decreased." (PMID 38629068, 2024). "Activation of ligand-independent EPHB4 can lead to cell proliferation and tumor transformation, while ligand-dependent activation induces cell death in certain tumours." (PMID 38803845, 2024). "This methylation profile negatively correlated with patients’ prognoses, therefore highlighting a tumor-suppressive effect of EPHB4." (PMID 38612645, 2024). "Other in vivo findings from orthotopic xenografts demonstrated improved inhibition of tumor growth when EPHB4 inhibition was combined with Gemcitabine chemotherapy." (PMID 39839790, 2024). "Inhibition of EPHB4 combined with radiation can modulate the microenvironment response post-radiation, contributing to increased tumor control in PC." (PMID 38095640, 2023). "Subsequently, a range of Eph receptors have been identified as preferentially expressed on tumours, of which EphA2, EphA3, and EphB4 have been a particular focus for therapeutic targeting." (PMID 36830852, 2023). "Initial studies reported that soluble EPHB4 blockers, inhibiting the ephrin-B2 forward signaling in venous endothelial cells and the backward signaling in the arterial endothelium, diminish tumor growth." (PMID 36769332, 2023). "EphB4 is a putative tumour suppressor gene in colorectal cancer, since its expression is commonly decreased or deleted." (PMID 36830852, 2023). "Knocking down EFNB1 or EPHB4 also significantly inhibited cancer cell migration and invasion but their overexpressing had the opposite effects in both normal and tumor cells." (PMID 38097539, 2023). "In vivo data from orthotopic xenografts showed enhanced tumor growth retardation with the addition of EPHB4 inhibition in combination with gemcitabine." (PMID 36769332, 2023). "Vasgene (Los Angeles, CA, USA) and CNIO Biotechnology (Madrid, Spain) have both explored EphB4 and ephrinB2 as promising targets because of their crucial involvement in the formation of tumour vasculature." (PMID 36830852, 2023). "This is reversed by stimulating overexpressed EphB4 with the soluble ephrin-B2 ligand, demonstrating the kinase-dependent tumour suppressor properties." (PMID 36830852, 2023).
tumor (continued). "Taken together, this study presents the first proof that exosomal M6PR and EphB4 play essential roles in tumor angiogenesis and malignancy, and that serum M6PR is a novel prognostic marker for ESCC patients." (PMID 36632458, 2023). "When combined with bevacizumab, the Vasgene mAbs 131 and 47 elicit tumour shrinkage in xenograft models via the degradation of EphB4, blocking tumour vasculature and slowing tumour progression." (PMID 36830852, 2023). "EFNB2-promoted tumor growth in the LM and liver injection models was significantly reduced after the inhibition of EPHB4 by siRNA and NVP-BHG712." (PMID 36376513, 2023). "In a mouse xenograft model, decreasing EphB4 expression in colon cancer cells led to increased tumour growth." (PMID 36830852, 2023). "In the MEER tumor model, complete knockout of EphB4 on cancer cells similarly resulted in a significant enhancement (p = 0.0006) in mean tumor volume compared to the control cohort (198.8 mm3 in control to 1024 mm3 in EphB4 KO)." (PMID 35725568, 2022). "The mean tumor volume in the EphB4 dominant-negative group was 2.19-fold higher than the control group at day 42 post-implantation." (PMID 35725568, 2022). "This would likely render EphB4 signaling on the cancer cell irrelevant while the drug is left to target ephrinB2 tumor-promoting effect on the tumor cells and within the vascular compartment of the TME." (PMID 35725568, 2022). "Enhanced apoptosis (2.5-fold) was also found in the CD8 + T cell population as represented by CD8 + Cleaved caspase 3+ cells in the EphB4 knockdown tumors, restricting their survival in the tumor milieu." (PMID 35725568, 2022). "Our research group and others have demonstrated that inhibiting EphB4-ephrinB2 interaction with a soluble protein or a plasmid-based derivative of peptide yields tumor growth retardation, but the magnitude of response is minimal and transient, at best." (PMID 35725568, 2022). "We observe that manipulating the EphB4 intracellular domain on cancer cells accelerates tumor growth and angiogenesis." (PMID 35725568, 2022). "We observe that EphB4 knockdown on the cancer cells accelerates tumor growth and promotes angiogenesis." (PMID 35725568, 2022). "High EPHB4 expression positively correlated with histological tumor grade, adverse clinical disease stage, post-menopausal stage of the patient, dedifferentiation, myometrial invasion, ER expression, and poor survival rates in EC tissue samples." (PMID 35328669, 2022). "Here, compartmental targeting of EphB4 and ephrinB2 in HNSCC cancer cell and endothelial compartments suggests that ephrinB2 acts as a tumor promoter and EphB4 as a tumor suppressor." (PMID 35725568, 2022). "In order to test the effect of EPHB4 on the tumor formation, an EPHB4 stable knockdown K562 cell line and EPHB4 rescue K562 cell line were established." (PMID 35689424, 2022). "The discordance between the TCGA data and our in vivo findings can be attributed to the fact that in our study, EphA4 was upregulated only when EphB4 was knocked down on the tumor cells." (PMID 35725568, 2022). "Our data showed that implantation of Moc2 EphB4 KO tumors in DEREG mice resulted in a significant 2-fold reduction in tumor volume compared to the tumors implanted in control mice." (PMID 35725568, 2022). "To reverse the tumor growth mediated by EphA4, we used a multi-target tyrosine kinase inhibitor, Dasatinib, in the EphB4 knockout tumor-bearing mice." (PMID 35725568, 2022). "Our study demonstrates how the compensatory mechanisms by upregulated EphA4 come into the concert when the preferred binding partner of ephrinB2, EphB4, is lost and by inhibiting EphA4 signaling, tumor growth inhibition can be effectively restored in HNSCC." (PMID 35725568, 2022). "Further substantiating a cancer cell-intrinsic tumor-suppressive effect of the EphB4 intracellular domain, an IncuCyte cell growth assay established that EphB4 dominant-negative cells increase cell growth compared to the control group." (PMID 35725568, 2022).
tumor (continued). "Among the most consistently upregulated EphB receptors is EphB4, which—similar to its ligand, ephrinB2—has consistently been detected in a wide variety of human tumor cell lines." (PMID 35163601, 2022). "Inhibition or downregulation of EphB4 was found to reduce the cancerogenic activity of multiple tumor types in vitro and in vivo." (PMID 35163601, 2022). "Subsequently, the PDGF-BB ligand promotes the direct activation of PDGFRβ and indirect activation of EPHB4, which eventually stimulates Akt and Erk1/2 signaling pathways that enhance tumor cell survival and proliferation, respectively." (PMID 35563562, 2022). "EphrinB2 was present on endothelial cells and for most patients in the tumor epithelial cells, whereas EphB4 was present, albeit with variable frequency, on tumor epithelial cells of all the patients, on endothelial cells, and on fibroblasts." (PMID 35725568, 2022). "EphB4 cancer cell loss also triggers compensatory upregulation of EphA4 and T regulatory cells (Tregs) influx and their targeting results in reversal of accelerated tumor growth mediated by EphB4 knockdown." (PMID 35725568, 2022). "The EphB4 dominant-negative tumors, on the other hand, showed a significant increase in tumor growth in a time-dependent manner." (PMID 35725568, 2022). "Of note, the intracellular signaling domain of EphB4 (or forward signaling) plays a central role in mediating the tumor-promoting effects." (PMID 35725568, 2022). "An increase in tumor growth mediated by EphB4 downregulation on cancer cells, however, can be overcome either by genetic ablation of Tregs or by pharmacologic inhibitors of tyrosine kinase receptors." (PMID 35725568, 2022). "Live imaging of the tumor vessels, in two modalities (chronic cranial window and dorsal skinfold chamber), revealed large, well perfused EphB4 tumor vessels." (PMID 35163601, 2022). "As levels of both EphB4 and its ligand ephrinB2 have been found to be significantly elevated in malignant glioma, further illumination of their role in tumor angiogenesis and possible resistance towards antiangiogenics is required." (PMID 35163601, 2022). "Within the TME, we find that EphB4 acts as a tumor suppressor in both paracrine and autocrine fashion." (PMID 35725568, 2022). "EphB4 is a high-affinity binding receptor for ephrinB2; and if ephrinB2 is a master tumor promoter within the TME, then it is sensible to upregulate EphB4 so its extracellular domain can be used for reverse signaling by ephrinB2." (PMID 35725568, 2022). "In contrast to ephrinB2, EphB4 was ubiquitously expressed in the cancer cells across the different tumor models." (PMID 35725568, 2022). "This study investigates the effects of targeting EphB4-ephrinB2 interactions separately in the HNSCC tumor and its microenvironment." (PMID 35725568, 2022). "In HNSCC, response to EphB4-ephrinB2 inhibitors has been modest at best, and tumor growth delay is only noted when combined with radiation therapy." (PMID 35725568, 2022). "We also used a serial tumor challenge assay to evaluate the persistence of the antitumor activity of EPHB4-CAR-T cells." (PMID 33816783, 2021). "EPHB4 upregulation were correlated with increased clinical stage, tumor dedifferentiation, deeper myometrial invasion, and low OS." (PMID 34445116, 2021). "Controversial roles of proteins in different cancer types have been reported in previous studies; for instance, EPHB4 was described as an oncogene in some cancers and as a tumor suppressor in other cancers." (PMID 34829812, 2021). "We also showed increased cytoplasmic expression of EphB4 in tumor cells in treatment naïve tumor tissue from PDAC cases by IHC, which further supports our findings." (PMID 34298619, 2021). "In vivo studies directed against EphB4 using albumin-conjugated soluble EphB4 in combination with gemcitabine showed a significant decrease in tumor growth in orthotropic xenografts." (PMID 34298619, 2021).
tumor (continued). "The EphB4 status in carcinoma cells was positively correlated with tumor size, T factor, and Ki-67 labeling index in all patients and was associated with poor relapse-free survival in EGFR mutation-positive patients." (PMID 34445227, 2021). "Other studies reported that EPHB4 was gradually overexpressed, from preneoplastic lesions to gastroesophageal cancers, and was correlated positively with advanced tumor stage." (PMID 34445116, 2021). "Erythropoietin-producing human hepatocellular B4 (EPHB4) regulates a series of tumour functions involving tumourigenesis, cancer cell attachment and metastasis." (PMID 34539874, 2021). "EphB4 immunoreactivity was positively correlated with T factor (p = 0.0135), tumor size (p = 0.0027), and Ki-67 labeling index (LI) (p = 0.0004)." (PMID 34445227, 2021). "In conclusion, we investigated the on‐target/off‐tumor toxicity of PB‐mediated EPHB4‐CAR‐T cells using a lymphodepleted NHP model." (PMID 34123382, 2021). "In parallel, inhibition of EphrinB2/EphB4 forward signaling using soluble EphB4, which binds and sequesters the EphrinB2 ligand, resulted in a moderately decreased tumor growth of U48484 cells in an orthotopic allograft." (PMID 34440844, 2021). "This molecule, termed bi-directional ephrin agonist peptide (BIDEN-AP), can inhibit ephrin-B2 endothelial cell angiogenic signaling, while also activating EphB4 dependent tumor-suppressive signaling in tumor cells." (PMID 33634116, 2021). "EphB4 expressing on the tumor cells also interacts with ephrinB2 expressed on tumor vasculature to promote tumor angiogenesis." (PMID 34298619, 2021). "It is thus highly likely that EphB4 targeted therapy in spontaneous tumor models will prevent tumor development and progression." (PMID 34298619, 2021). "In the context of cancer therapy, blocking the mobilization of hematopoietic stem/ progenitor cell by inhibiting EphB4-ephrin-B2 communication also resulted in reduced infiltration of the hematopoietic stem/progenitor cells into murine tumor models." (PMID 33634116, 2021). "In contrast, the small molecule dasatinib, which inhibits both EphB4 and its partner PDGFRβ, resulted in a significant inhibition of in vitro tumor cell viability as well as decreased in vivo tumor growth and significantly prolonged survival." (PMID 34440844, 2021). "Masood found that decreased EphB4 expression results in a significant inhibition of tumour growth in xenograft models." (PMID 34539874, 2021). "In a large series of tissue specimens from CRC patients, scientists have demonstrated that from normal colon mucosa to preneoplastic lesions, to malignant tissues, to the tumor invasion front, to metastasis, EPHB4 expression is progressively reduced." (PMID 34445116, 2021). "Irrespective of the type of antibody used, immunohistochemical staining for EphB4 was primarily present in tumor cells throughout the tumor tissue cores." (PMID 32751634, 2020). "This confirmed the conclusion that EphB4-ephrinB2 reverse signaling is responsible for increased tumor growth as well as decreased tumor vascularization and perfusion." (PMID 33153234, 2020). "Conversely, increasing evidence supports the idea that ligand-dependent EFNB2/EphB4 forward signaling is tumor suppressive." (PMID 31949258, 2020). "Using a multi-scalic and multi-modal in vivo imaging approach, we found EphB4 to be a promotor of tumor growth and hypoxia and an inhibitor of tumor vascularization and perfusion." (PMID 33153234, 2020). "Erythropoietin-producing hepatocyte receptor B4 (EphB4) is a member of the tyrosine kinase family and plays a pivotal role in tumor progression." (PMID 32801343, 2020). "With regard to tumor perfusion, measured by i.v. injection of the radiotracer [64Cu]Cu-ETS and subsequent radioluminography of tumor sections, we observed a decrease in tumor perfusion by overexpression of EphB4 in the vehicle group." (PMID 33153234, 2020).